CCL4 (C-C motif chemokine ligand 4)
Diseases named in the same sentence as CCL4 in open-access papers (continued):
Sharing a sentence is not in itself a finding about the gene and the disease.
melanoma (continued). "In humans, the chemokines CCL2, CCL3, CCL4, CCL5, CXCL9, and CXCL10 have been associated with increased T cell infiltrates in melanomas, and the same chemokines were confirmed to attract human CD8+ T cells in vitro." (PMID 34454518, 2021). "Basophil release of chemokines, such as CCL3 and CCL4, are also thought to play a role in attracting T cells into tumors, which in a melanoma mouse model, led to tumor rejection." (PMID 32645919, 2020). "In this context, it was shown that an active Wnt-β-catenin signaling in melanoma cells suppresses production of CCL4 (C-C motif chemokine ligand 4) and consequently reduces migration and accumulation of CD103+ DCs in the TME." (PMID 32132993, 2020). "In β-catenin-positive melanoma cells, secretion of CCL4 and other chemokines was reduced, with insufficient recruitment of specific DCs into the tumor area and defective host priming of antigen-specific T cells." (PMID 31921125, 2019). "High expression of CCL4 and CCL5 are associated with better outcome in melanoma, endometrial, and colorectal cancer, but with worst outcome in renal cancer." (PMID 30873179, 2019). "For example, in melanoma, the upregulation of chemokine genes, such as Ccl2, Ccl3, Ccl4, Ccl5, Cxcl9, and Cxcl10, in the tumor microenvironment correlates with the influx of activated T cells into the tumor supporting the antitumor immune response." (PMID 29410666, 2018). "The CD103+ DCs elevated CXCL9 and CXCL10 in order to further attract T cells to infiltrate the tumor, and deletion of CCL4 in the melanoma cells abrogated T cell infiltration." (PMID 29109732, 2017). "Based on these data, we next set out to determine what characteristics of lung cancer may contribute to the higher levels of CD8+ T cell–dependent CCL3 and CCL4 production compared with melanoma." (PMID 40553564, 2025). "Immunohistochemical analyses and database studies have shown that higher CCL4 levels correlate with improved survival in primary melanoma patients, while T-cell single-cell RNA sequencing in metastatic melanoma patients suggests its association with durable responses to ICB." (PMID 40361472, 2025). "In melanoma, colorectal cancer, and non-small cell lung carcinoma (NSCLC), the reduced recruitment of intra-tumoral CD103+ DCs was caused by β-catenin-mediated inhibition of chemokine CCL4 production." (PMID 38926350, 2024). "The combination of pharmacologic sEH inhibition and immune checkpoint blockade resulted in decreased gene expression of the pro-inflammatory cytokines Il-6, Cxcl1, Tnfα, Ccl2, and Ccl4 compared to control after 11 d of treatment in the B16F10 melanoma tumor tissue." (PMID 38330013, 2024). "IL-8 and CCL4 were selected based on previous findings showing that their circulating levels could predict response to therapy and/or OS of melanoma patients treated with immunotherapy or targeted therapy." (PMID 39143551, 2024). "Moreover, in melanoma animal models, this reduction in CCL4 impairs DC recruitment and resulting anti-tumor immunity." (PMID 36275666, 2022). "Whether the reduction in CCL4 secretion works alone or in tandem with the depletion of other soluble factors is hard to say, since conditioned medium from melanoma cells with active β-catenin signaling is depleted of other soluble factors as well." (PMID 35385679, 2022). "Wnt signaling was also correlated with immune exclusion in melanoma by reducing the secretion of CCL4, a chemokine that attracts the immune cells It was also involved in melanoma progression by regulating cell proliferation and invasion and promoting resistance to targeted therapies." (PMID 35646893, 2022). "This discrepancy may be due in part to decreased secretion of chemokine CCL4 by melanoma cells arising from active β-catenin signaling, resulting in hampered CD103+ DC tumor infiltration and impeded CD103+ DC chemotaxis." (PMID 35385679, 2022).
melanoma (continued). "A recent study on melanoma found CCL4-expressing CD8+ T cells were robust expressors of Lag-3, which supports the notion that this subset might be exhausted." (PMID 35720272, 2022). "However, in a genetically engineered mouse model of melanoma, defective expression of CCL4 (macrophage inflammatory protein-1-beta), a ligand for CCR5, led to reduced DC recruitment to tumors." (PMID 33603130, 2022). "Our results also support the link of melanoma with CCL4, CXCL10, and CCL510." (PMID 36443341, 2022). "Furthermore, the investigators found that the Wnt signaling target gene ATF3–which also binds at the promoter region of the CCL4 gene—was expressed at higher levels in the β-catenin activated melanoma tumors." (PMID 33672668, 2021). "In particular, the chemokine genes CCL4, CCL5 and CXCL9, which were found to be diminished in HS versus LS cases from TCGA, were previously reported to be part of a gene signature associated with enhanced T cell infiltration in melanoma." (PMID 33806316, 2021). "Thus, it has been shown that the expression of CCL4, CCL5, and CXCL10 in melanoma metastases is associated with the recruitment of CD8+ T cells." (PMID 30984181, 2019). "It has been shown that high levels of chemokines CCL3, CCL4, and CXCL8 in pre-treatment tumor specimens were associated with worse patient overall survival after anti-CTLA4 and Carboplatin/paclitaxel treatment in melanoma." (PMID 30873179, 2019). "In melanoma, it has been demonstrated that up regulation of expression of several chemokine genes such as Ccl2, Ccl3, Ccl4, Ccl5, Cxcl9, and Cxcl10 in the tumor microenvironment correlates with the recruitment of activated effector T cells to the tumor increasing antitumor immunity." (PMID 27876058, 2016). "Besides, tumor-infiltrating granulocytes and monocellular myeloid-derived suppressor cells can release CCL4 in surplus to act on CCR5 receptors on melanoma and lymphoma cancer cells, thus recruiting a large number of T regulatory cells and promoting the generation, growth, and metastasis of cancer." (PMID 37593100, 2023). "Moreover, macrophages are a major source of CCL2, CCL3, CCL4, CCL5, CXCL9 and CXCL10, which are important chemokines that induce T lymphocyte chemotaxis, and which we find in association with stromal activation in actual melanomas." (PMID 28448494, 2017). "An intravenous infusion of the collagen-binding domain of von Willebrand factor conjugated with CCL4 recruited more CD103+ and CD8+ T cells into the a melanoma and breast cancer mouse model and improved the immunotherapy’s efficacy." (PMID 38928238, 2024). "In melanoma and HCC, a decrease in CCL4 and CCL5, leads to a defective recruitment of dendritic cells and consequently impaired T-cell activity and immune escape." (PMID 39008536, 2024). "Here, plasma levels of IL-8, CCL4, osteopontin, LIF and BDNF were determined at baseline (T0), after 2 months of therapy (T2) and, when feasible, at progression (TP), in 70 melanoma patients treated with BRAF and MEK inhibitors." (PMID 39143551, 2024). "Immune suppressive effects of increased CCL3 have been observed in melanoma and higher levels of CCR5 ligands, CCL3, CCL4 and CCL5, correlated with accumulation of CCR5 + MDSCs in melanoma lesions and tumor progression." (PMID 37964379, 2023). "The same study also showed an enrichment of CCR5+ MDSCs and increased concentration of the cognate ligands, i.e., CCL3, CCL4, and CCL5, in melanoma specimens compared to matched serum." (PMID 33603130, 2022). "TGF-β-expressing B cells in the melanoma tumor microenvironment assembled in clusters and interacted with T cells via lymphoid recruitment (SELL, CXCL13, CCL4, CD74) signals and with Tregs via CD47:SIRP-γ, and FOXP3-promoting Galectin-9:CD44." (PMID 35909944, 2022). "In mouse melanoma tumors, non-coding control plasmid DNA electrotransfer induces the secretion of CCL3 after 4 and 24 h and CCL4 after 4 h." (PMID 36297532, 2022).
melanoma (continued). "Under the activation of WNT/β-catenin signaling, activating transcription factor 3 (ATF3)-mediated CCL4 downregulation is considered to reduce the migration of CD103+ dendritic cells into the tumor and reduce CD8+ TILs in melanoma." (PMID 34359568, 2021). "By LASSO Cox regression analysis, we constructed a prognosis model based on 5-mRNA (SRGN, IDO1, RARRES3, CCL4, HLA-DPB1), which has great predictive value for the overall survival of melanoma." (PMID 34805163, 2021). "In a melanoma mouse model and patients with melanoma, the CCR5+ MDSCs accumulated in tumor tissues were positively correlated with the upregulation of CCL3, CCL4, and CCL5." (PMID 34527668, 2021). "An additional study reports a significant expression change of six chemokines (namely, CCL2, CCL3, CCL4, CCL5, CXCL9, and CXCL10) related to the lymphocyte infiltration in the melanoma tissue." (PMID 33302400, 2020). "Further dissection of cluster 1 induced in IL-32–treated tumors showed significantly increased protein levels of the CCR5-binding chemokines CCL3, CCL4, CCL5, and CXCL2, corroborating the observations in IL-32hi human melanoma." (PMID 32841222, 2020). "Expression was confirmed to be significantly different in melanoma compared to the healthy controls, for IL-1Ra (recognized as ILRn by GEPIA2), IL-7, MIP-1a (recognized as CCL3 by GEPIA2), and MIP-1b (recognized as CCL4 by GEPIA2)." (PMID 33302400, 2020). "Clinical data indicate that CCR5 ligands, CCL4, and CCL5, can promote anti-melanoma immune response." (PMID 30873179, 2019). "This plasmablast-like phenotype can be reconciled in human melanomas where plasmablast-like cells also express T cell-recruiting chemokines CCL3, CCL4, CCL5." (PMID 31519915, 2019). "Furthermore, intra-tumour delivery of CCL4 has been reported to enhance CD103+ DC and CD8+ T-cell recruitment in melanoma and breast cancer models." (PMID 40361472, 2025). "Four of these Top HRLs are recognized by 2 of the Top HRs and represent ligand-receptor pairs that have been previously identified as crucial mediators of T and B cell trafficking in melanoma: CXCL10 and CXCL9 are ligands for CXCR3; and CCL4 and CCL5 are ligands for CCR5." (PMID 34454518, 2021). "Recent evidence suggests that CCL4 and CCL5, but not CXCL9-11, are positively associated with survival in melanoma." (PMID 32841222, 2020). "As an example, immune exclusion mediated by activation of the WNT–β-catenin pathway was observed in melanoma when expression of CCL4 was inhibited and DCs were no longer recruited into the tumor." (PMID 31921125, 2019). "Unlike that observed in melanoma, the accumulation of T lymphocytes was not due to the production of CCL4 by the tumors." (PMID 31105882, 2019). "Moreover, it was recently found that CCR5 is expressed on MDSC in RET transgenic melanoma-bearing mice and melanoma patients, playing an important role in their recruitment to the tumor microenvironment via the CCR5 ligands (CCL3, CCL4, and CCL5)." (PMID 29942309, 2018). "Interestingly, CCR5 is more highly expressed on tumor infiltrating monocytic MDSC than on peripheral cells and high concentrations of CCL3, CCL4, and CCL5 are found in melanoma lesions, potentially explaining the enrichment of CCR5+ MDSC in tumors." (PMID 30420855, 2018). "CCL4 and CCL3 may mediate the recruitment of CD8+ T cells and regulatory T cells within melanoma lesions." (PMID 29157311, 2017). "Eva et.al found CCL4 secreted by tumor-infiltrating granulocytic and monocytic myeloid-derived suppressor cells (MO-MDSCs) recruit high numbers of regulatory T cells (Tregs) via CCR5 in lymphoma and melanoma." (PMID 28404909, 2017). "Finally, higher proportions of tumor-reactive T cells co-expressing CCL4, IFN-γ, and TNF-α were detected in melanoma patients with favorable clinical responses to α-CTLA-4 treatment." (PMID 21203522, 2010). "Checkpoint-inhibitor-unresponsive melanomas lacked CCL4 (a ligand for CCR8—but also for CCR5)." (PMID 37759462, 2023).
melanoma (continued). "In melanoma cells, activation of the WNT/Β-catenin pathway reduces the number of tumor-infiltrating lymphocytes (TILs) because activation of this pathway decreases the expression of chemokine C-C motif ligand 4 (CCL4), which is essential for tumor infiltration by DCs." (PMID 36119072, 2022). "A study of individual CSF samples from 22 patients with melanoma brain metastases and 5 disease-free controls found that Chemokine CCL22 and cytokines IL-1α, IL-4, and IL-5 were reduced in most samples, whereas a subset of molecules including CXCL10, CCL4, CCL17, and IL8 increased expression." (PMID 36527157, 2022). "Further, analysis of clusters identified within the melanoma patient set comparing patient outcome suggests that suppression of IL-1α, IL-4, IL-5, and CCL22, with concomitant elevation of CXCL10, CCL4, and CCL17, may correlate with more aggressive development of brain metastasis." (PMID 36527157, 2022). "Taken together, we assumed that CCL4 and CCL5 may be potent biomarkers and targets for melanoma." (PMID 32508531, 2020). "Indeed, CCL4 is an important chemokine involved in the recruitment of DCs in the tumor microenvironment through its receptor CCR5 and the lack of CCL4 has been described as a hallmark of cold melanoma tumor." (PMID 32580431, 2020). "For example, in melanoma, the lack of CCR5 ligands (CCL3, CCL4, CCL5) and CXCR3 ligands (CXCL9 and CXCL10) has been associated with limited infiltration of antigen-specific T cells." (PMID 30873179, 2019).
atherosclerosis (43 papers, 2012 to 2025). A disease characterized by the build-up of fatty material and calcium deposition in the arterial wall resulting in partial or complete occlusion of the arterial lumen. "Elevated levels of CCL4 in the plasma of patients with atherosclerosis indicate a higher risk of stroke and cardiovascular events for those with higher CCL4 levels." (PMID 40809841, 2025). "The roles of chemokine CC motif ligand 4 (CCL4) and its receptor are associated with diabetes mellitus (DM) and atherosclerosis cardiovascular diseases." (PMID 27553774, 2016). "CCL3 and CCL4 are the inflammatory chemokines associated with atherosclerosis." (PMID 40824771, 2025). "In clinical practice, atherosclerosis is associated with elevated levels of circulating CCL4." (PMID 38275601, 2023). "In summary, as an important chemokine, CCL4 demonstrates significant pathological relevance in both Sjögren’s syndrome and atherosclerosis, indicating its potential as a therapeutic target for these two diseases." (PMID 40809841, 2025). "Atherosclerosis is characterized as a chronic inflammatory condition, with CCL4 detectable in T cells, smooth muscle cells, and macrophages within atherosclerotic plaques, and further upregulated in vulnerable plaques." (PMID 40809841, 2025). "Experimental data from animal models of atherosclerosis suggest that direct inhibition of CCL4 stabilises atherosclerotic plaques and reduces endothelial cell and macrophage activation." (PMID 39512689, 2024). "The atherosclerosis-related CCL4 gene is one of the ligands for the C-C chemokine receptor ligand type 5." (PMID 38275601, 2023). "C-C motif chemokine receptor 5 (CCR5) and its ligands CCL3 (MIP-1α), CCL4 (MIP-1β), and CCL5 (RANTES) also associate and contribute to the initiation and progression of atherosclerosis and related cardiovascular diseases." (PMID 36035865, 2022). "By providing an inflammatory microenvironment, CCL4 induces cell adhesion to endothelial cells through oxidative stress and tends to augment atherosclerosis and vascular injury." (PMID 34975900, 2021). "In view of the potential future impact, this study aimed to investigate the in vivo and in vitro role of CCL4 in atherosclerosis and to evaluate the feasibility of the use of CCL4 antibodies to retard the progression of atherosclerosis." (PMID 32911750, 2020). "In this study, the direct inhibition of CCL4 with specific antibodies decreased vascular inflammation, reduced the plaque area, and stabilized the vulnerability of atheroma in a mouse model of atherosclerosis in vivo." (PMID 32911750, 2020). "Our findings support the role of CCL4 in atherosclerosis and provide a rationale for a novel anti-atherosclerosis strategy targeting CCL4." (PMID 32911750, 2020). "The upregulation of circulating CCL4 levels was also observed in patients with type 2 DM and/or clinical atherosclerosis cardiovascular diseases." (PMID 27553774, 2016). "Although increasing evidence supports the potential role of CCL4, the mechanistic insights and clinical impact of CCL4-related atherosclerosis cardiovascular disease should be further explored." (PMID 27553774, 2016). "CCL4 was also upregulated in vulnerable atherosclerosis plaques and was expressed by T cells in advanced atherosclerotic lesions in stroke patients." (PMID 27553774, 2016). "Therefore, CCL4 not only plays a significant role in Sjögren’s syndrome but also has a key function in the pathophysiological process of atherosclerosis." (PMID 40809841, 2025). "In the context of atherosclerosis, CCL4 also plays a significant role." (PMID 40809841, 2025). "In addition to Dpp4, there was an upregulation of a number of inflammation‐related genes including Card8, Card16, Gzma, Prf1, Il2rg, Il32, Cd52, and Ccl4 in CD4+ T cells isolated from patients with atherosclerosis." (PMID 36683148, 2023). "However, a recent study on atherosclerosis reported a strong relation between CCL4, IL-6, and tumor necrosis factor α (TNF-α)." (PMID 36290379, 2022).